GET1 (guided entry of tail-anchored proteins factor 1)
Description:
Required for the post-translational delivery of tail-anchored (TA) proteins to the endoplasmic reticulum (ER). Together with CAMLG/GET2, acts as a membrane receptor for soluble GET3/TRC40, which recognizes and selectively binds the transmembrane domain of TA proteins in the cytosol. Required to ensure correct topology and ER insertion of CAMLG.
Synonyms: CHD5; WRB
Tractability: Antibody: UniProt predicts a signal peptide or a membrane-spanning region. PROTAC: ubiquitination databases record sites on it.
Gene: Protein-coding gene on chromosome 21 (39,377,698 to 39,428,528, forward strand). Ensembl gene ENSG00000182093.
Subcellular location: Endoplasmic reticulum membrane
Pathways (Reactome):
Protein localization: Insertion of tail-anchored proteins into the endoplasmic reticulum membrane
Gene Ontology:
Molecular function: protein binding; protein-membrane adaptor activity
Biological process: protein insertion into ER membrane; protein stabilization; tail-anchored membrane protein insertion into ER membrane; establishment of protein localization to membrane
Cellular component: endoplasmic reticulum membrane; GET complex; nucleus
Genetic constraint (gnomAD): Loss-of-function variants: 19 observed, 22.54 expected, observed/expected ratio (o/e) 0.84, 90% interval 0.59 to 1.24. The upper end of that interval is the gene's LOEUF score, 1.24, which puts it in group 5 of 6, group 1 being the genes least tolerant of losing a copy. Missense variants: 204 observed, 227.47 expected, observed/expected ratio (o/e) 0.9, 90% interval 0.8 to 1.01. Synonymous variants: 92 observed, 87.47 expected, observed/expected ratio (o/e) 1.05, 90% interval 0.89 to 1.25.
Homologues: Orthologues: chimpanzee GET1 (100% identical), pig GET1 (97% identical), dog GET1 (96% identical), guinea pig GET1 (95% identical), mouse Get1 (93% identical), zebrafish rps3 (22% identical), Drosophila melanogaster RpS3 (20% identical), Caenorhabditis elegans rps-3 (17% identical). Paralogues in human: RPS3 (23% identical).
Diseases named in the same sentence as GET1 in open-access papers:
GET1 is named in the same sentence as 9 diseases in open-access papers, as found by Europe PMC text mining. Sharing a sentence is not in itself a finding about the gene and the disease. The quoted sentences say what the papers report.
congenital heart disease (3 papers, 2005 to 2021). A heart disease that is present at birth. "With regard to illness, the genomic locus of the GET1 gene has been mapped to the congenital heart disease region of human chromosome 21." (PMID 35008565, 2021). "Yet, a clear correlation between GET1 and its role in the development of cardiac defects and congenital heart disease has not been established in humans." (PMID 35008565, 2021).
bladder cancer (2 papers, 2020 to 2021). "The latest research suggests that the CRISPReader system that regulates gene transcription can effectively target and inhibit bladder cancer cells by sensing transcription factors such as c-Myc and Get-1 in the cell." (PMID 34124154, 2021). "For example, the UPII promoter was inactive in highly malignant bladder cancer lines, although the Get1 transcription factor was expressed at high levels." (PMID 33127914, 2020). "In theory, both c-Myc and Get1 should have a relative high expression level only in bladder cancer cells." (PMID 33127914, 2020). "However, the expression levels of both c-Myc and Get1 increased with increases in the malignancy of bladder cancer." (PMID 33127914, 2020). "In contrast, the minigene circuits were only regulated by c-myc and Get1 transcription factors, and therefore they could respond precisely to the malignant transformation of bladder cancer cells." (PMID 33127914, 2020).
brain injury (1 paper, 2025). Acute and chronic (see also brain INJURIES, CHRONIC) injuries to the brain, including the cerebral hemispheres, CEREBELLUM, and brain STEM. "In our previous study, we demonstrated that mice overexpressing astrocytic ET-1 (GET-1) exhibited more severe neurological deficits coupled with BBB integrity impairment, which contributed significantly to more severe ischemic brain injury." (PMID 40453657, 2025).
Stroke (1 paper, 2019). Sudden impairment of blood flow to a part of the brain due to occlusion or rupture of an artery to the brain. "However, it is unclear whether the observed severe brain damage in GET-1 mice post stroke is due to ET-1 dysregulation of neurogenesis by altering the stem cell niche." (PMID 31733648, 2019).
GET1 also shares sentences with these, for which no sentence is quoted: Strabismus (3 papers); Down syndrome (2); Esotropia (2); trisomy 21 (1); tumor (1).